SH2D5 (SH2 domain containing 5)
Description:
May be involved in synaptic plasticity regulation through the control of Rac-GTP levels.
Tractability: No criterion of Open Targets' tractability assessment is met for any kind of drug.
Gene: Protein-coding gene on chromosome 1 (20,719,724 to 20,732,837, reverse strand). Ensembl gene ENSG00000189410.
Subcellular location: Postsynaptic density
Subcellular location (Human Protein Atlas): Cytosol
Gene Ontology:
Cellular component: postsynaptic density
Genetic constraint (gnomAD): Loss-of-function variants: 45 observed, 45.62 expected, observed/expected ratio (o/e) 0.99, 90% interval 0.78 to 1.26. The upper end of that interval is the gene's LOEUF score, 1.26, which puts it in group 5 of 6, group 1 being the genes least tolerant of losing a copy. Missense variants: 538 observed, 561.13 expected, observed/expected ratio (o/e) 0.96, 90% interval 0.89 to 1.03. Synonymous variants: 230 observed, 236.56 expected, observed/expected ratio (o/e) 0.97, 90% interval 0.87 to 1.09.
Homologues: Orthologues: chimpanzee SH2D5 (100% identical), macaque SH2D5 (98% identical), rabbit SH2D5 (91% identical), guinea pig SH2D5 (88% identical), mouse Sh2d5 (88% identical), rat Sh2d5 (88% identical), pig SH2D5 (86% identical), dog SH2D5 (82% identical), tropical clawed frog sh2d5 (40% identical), Caenorhabditis elegans nck-1 (8% identical), Drosophila melanogaster dock (8% identical). Paralogues in human: GRAP2 (13% identical), GRB2 (12% identical), GRAP (11% identical), SLA2 (11% identical), NCK2 (10% identical), SLA (10% identical), NCK1 (9% identical), DAPP1 (9% identical), GRAPL (6% identical).
Diseases named in the same sentence as SH2D5 in open-access papers:
SH2D5 is named in the same sentence as 20 diseases in open-access papers, as found by Europe PMC text mining. Sharing a sentence is not in itself a finding about the gene and the disease. The quoted sentences say what the papers report.
hepatocellular carcinoma (3 papers, 2023 to 2025). A malignant tumor that arises from hepatocytes. "The expression level of SH2D5 in the liver tissue of HBV-associated hepatocellular carcinoma (HCC) patients was significantly higher than that in adjacent tissues." (PMID 39775732, 2024). "STAT3, a member of the STAT protein family, has been reported to regulate NMDAR transcription and is regulated by SH2D5 in hepatocellular carcinoma." (PMID 40857409, 2025). "Previous studies have found that in HBV-related hepatocellular carcinoma, the expression of SH2D5 is abnormally upregulated, and it promotes the proliferation and metastatic ability of cells." (PMID 39775732, 2024). "It has been unraveled that SH2D5 expresses at a higher level in liver tissues sourced from patients with HBV-related hepatocellular carcinoma (HCC) relative to adjacent non-tumor tissues." (PMID 37187527, 2023).
lung adenocarcinoma (2 papers, 2023 to 2024). A carcinoma that arises from the lung and is characterized by the presence of malignant glandular epithelial cells. "Gene set enrichment analysis (GSEA) revealed that SH2D5 positively regulates the epithelial-mesenchymal transition (EMT) process in lung adenocarcinoma cells." (PMID 39775732, 2024). "Through loss-of-function and gain-of-function experiments, we revealed that overexpression of SH2D5 promotes the proliferation and migration abilities of lung adenocarcinoma cells." (PMID 39775732, 2024). "Subsequently, by conducting loss-of-function and gain-of-function experiments, we revealed that the overexpression of SH2D5 promotes the proliferation and migration of lung adenocarcinoma cells." (PMID 39775732, 2024). "Through analyzing the SH2D5 expression profiles, clinical features, and immune infiltration in lung adenocarcinoma (LUAD), the study was intended to discuss the correlations of SH2D5 with prognosis and immune infiltration in LUAD." (PMID 37187527, 2023). "Univariate analysis and Multivariate analysis of the correlation of SH2D5 expression with OS among lung adenocarcinoma." (PMID 37187527, 2023). "Finally, to gain a more comprehensive understanding of the expression patterns of SH2D5 in lung adenocarcinoma cells, we selected three cell lines that represent distinct genetic backgrounds." (PMID 39775732, 2024). "In our study, we utilized the AKT-specific inhibitor (MK-2206, 10μM) and activator (SC79, 10μM) to suppress or activate the AKT signaling pathway in lung adenocarcinoma cells with either overexpression or knockdown of SH2D5, in order to investigate whether the effects of SH2D5 could be reversed." (PMID 39775732, 2024).
bladder urothelial carcinoma (1 paper, 2023). "Relative to non-cancerous tissues, SH2D5 expression was elevated in most tumors, such as bladder urothelial carcinoma, cholangiocarcinoma, esophageal carcinoma, head and neck squamous cell carcinoma, renal papillary cell carcinoma, LUAD, lung squamous cell carcinoma, etc.." (PMID 37187527, 2023).
brain injury (1 paper, 2025). Acute and chronic (see also brain INJURIES, CHRONIC) injuries to the brain, including the cerebral hemispheres, CEREBELLUM, and brain STEM. "We also detected increased expression of SH2D5 in the temporal lobe tissues of patients with TLE compared with those of control patients who experienced traumatic brain injury (TBI) but did not exhibit epilepsy symptoms." (PMID 40857409, 2025).
epilepsy (1 paper, 2025). A brain disorder characterized by episodes of abnormally increased neuronal discharge resulting in transient episodes of sensory or motor neurological dysfunction, or psychic dysfunction. "Taken together, these findings suggest that Sh2d5 KO can reduce seizure susceptibility and alleviate epilepsy development." (PMID 40857409, 2025). "This study investigated the role of SH2D5 in epilepsy and the mechanisms underlying this role." (PMID 40857409, 2025). "To investigate the potential involvement of SH2D5 in epilepsy, we first assessed the localization of SH2D5 in epileptic brain tissues via immunofluorescence." (PMID 40857409, 2025). "A behavioral study was conducted on KA-induced epilepsy model and pentylenetetrazol (PTZ) kindling model to investigate the effect of SH2D5 on epilepsy development." (PMID 40857409, 2025). "We found that i.p. injection of fludarabine resulted in a significant increase in the protein expression of NMDARs in the hippocampi of Sh2d5-KO mice with KA-induced epilepsy." (PMID 40857409, 2025). "The change in SH2D5 expression in the epileptic brain indicates the potential involvement of SH2D5 in epilepsy." (PMID 40857409, 2025). "LFP analysis of mice with KA-induced epilepsy revealed that Sh2d5-KO mice treated with fludarabine presented significant increases in the frequency of SLEs and the duration of SLEs." (PMID 40857409, 2025). "We used IP-MS to identify proteins whose expression is modulated by SH2D5 in the context of epilepsy and revealed that SH2D5 interacts with a multitude of synapse-associated proteins, particularly those in the glutamatergic synaptic pathway." (PMID 40857409, 2025). "In the KA-induced epilepsy model, compared with control mice, Sh2d5-KO mice exhibited a prolonged latency to seizure onset and SE onset in the acute phase after KA administration." (PMID 40857409, 2025). "To further confirm that STAT1 functionally participates in the regulation of epilepsy by SH2D5, we performed a rescue experiment in which STAT1 was inhibited with fludarabine." (PMID 40857409, 2025). "SH2D5 protein expression in the hippocampus and cortex was elevated in mice with KA-induced epilepsy compared with control mice." (PMID 40857409, 2025). "Taken together, these findings suggest that SH2D5 regulates NMDAR-mediated synaptic transmission in epilepsy." (PMID 40857409, 2025). "Functionally, the protein levels of STAT1 and dimerized STAT1 were increased in the hippocampi of Sh2d5-KO mice with epilepsy." (PMID 40857409, 2025). "Our findings suggest that STAT1 is the key gene regulated by SH2D5 in mice with epilepsy." (PMID 40857409, 2025). "To investigate whether the upregulation of the SH2D5 protein contributes to the development of epilepsy, we examined its effect on epileptic activity in Sh2d5-KO mice." (PMID 40857409, 2025). "In addition, we confirmed the effect of Sh2d5 KO on epilepsy development in PTZ kindling model." (PMID 40857409, 2025). "KO of Sh2d5 increased STAT1 levels, inhibited NMDAR transcription, and alleviated epilepsy symptoms, while inhibiting STAT1 worsened seizures." (PMID 40857409, 2025). "In conclusion, our findings suggest that SH2D5 regulates autophagy in hippocampal neurons in the brain, thereby modulating the expression of STAT1 and subsequently influencing the transcription of NMDARs, ultimately affecting epilepsy-related behavioral phenotypes." (PMID 40857409, 2025). "Deletion of SH2D5 did not result in significant changes in the PPR but did alter the number and complexity of dendritic spines, suggesting that the probability of presynaptic glutamate release was unchanged but that synaptic remodeling was altered in epilepsy." (PMID 40857409, 2025).
lung carcinoma (1 paper, 2023). "Furthermore, enrichment analysis suggested that SH2D5 was associated with lung cancer and immunity." (PMID 37187527, 2023).
migraine (1 paper, 2023). "A larger study of epigenetic changes in SH2D5, NPTX2, COMT, GIT2, ZNF234, and SOCS1 genes is necessary to understand the processes of migraine chronicity and MOH development." (PMID 37298078, 2023).
non-small cell lung carcinoma (1 paper, 2023). A group of at least three distinct histological types of lung cancer, including non-small cell squamous cell carcinoma, adenocarcinoma, and large cell carcinoma. "The results showed that non-small cell lung cancer, pathways in cancer, primary immunodeficiency are differentially enriched in SH2D5 high expression phenotype of LUAD." (PMID 37187527, 2023).
temporal lobe epilepsy (1 paper, 2025). A localization-related (focal) form of epilepsy characterized by recurrent seizures that arise from foci within the temporal lobe, most commonly from its mesial aspect. "In temporal lobe samples obtained from patients with temporal lobe epilepsy (TLE) undergoing lesion resection, SH2D5 was also predominantly expressed in neurons." (PMID 40857409, 2025).
tumor (4 papers, 2018 to 2024). "Meanwhile, tumor immune estimation resource (TIMER) was adopted for correlation analysis between SH2D5 expression and immune infiltration in LUAD." (PMID 37187527, 2023). "In the meantime, some limitations exist that we fail to deeply explore the relevance of SH2D5 to tumor invasion due to the database and that in vivo and in vitro experiments are warranted for additional validation of our findings." (PMID 37187527, 2023). "By regulating STAT3 and VEGF signaling, SH2D5 might be involved in regulating YAP/TAZ activity during tumor angiogenesis." (PMID 33614496, 2020). "SH2 domain containing protein 5, or SH2D5, is a transcriptional target of YAP/TAZ and promotes tumor growth through interaction with transketolase, a regulator of the STAT3 signaling pathway." (PMID 33614496, 2020). "Additionally, we found that regulating the expression of SH2D5 influenced the phosphorylation levels of AKT, and the rescue experiments with AKT pathway activators/inhibitors partially reversed the tumor progression and EMT processes induced by SH2D5." (PMID 39775732, 2024). "Six genes were found to be altered in two tumours: MYO1A, DNAH11, SH2D5, ATM, MUC4 and ROS1." (PMID 29665859, 2018).
cancer (2 papers, 2023 to 2024). A tumor composed of atypical neoplastic, often pleomorphic cells that invade other tissues. "SH2D5 expression exhibited positive associations with the drug reactions of Staurosporine, while negative associations with anti-cancer drugs Crizotinib, Tamoxifen, Dolastatin 10, Vinorelbine, Vinblastine, Eribulin mesilate, Homoharringtonine, Tyrothricin." (PMID 37187527, 2023). "Sangerbox website and R language were applied for SH2D5 expression profiling in different cancers." (PMID 37187527, 2023). "This suggests that SH2D5 may play a crucial role in the metastasis of carcinomas." (PMID 39775732, 2024). "Based on the median SH2D5 gene expression, LUAD patients were divided into SH2D5 high expression and low SH2D5 expression groups, GSEA was used to reveal the dysregulated cancer characteristics in each group." (PMID 39775732, 2024). "Additionally, our study did not explore the different expression trends of SH2D5 in LUAD cell lines, which is an important aspect for understanding its functional significance in cancer biology." (PMID 39775732, 2024).
SH2D5 also shares sentences with these, for which no sentence is quoted: cholangiocarcinoma (1 paper); chronic headache (1); esophageal carcinoma (1); head and neck squamous cell carcinoma (1); Huntington disease (1); liver cancer (1); lung squamous cell carcinoma (1); primary immunodeficiency (1); renal papillary cell carcinoma (1).